IL15 (interleukin 15)
Diseases named in the same sentence as IL15 in open-access papers (continued):
Sharing a sentence is not in itself a finding about the gene and the disease.
renal carcinoma (8 papers, 2008 to 2024). A carcinoma arising from the epithelium of the renal parenchyma or the renal pelvis. "On the other hand, our recent data showed that IL-15 induces the differentiation of CD105+ renal cancer stem cells into epithelial cells that share several properties with normal tubular cells owing to the acquired production of their own IL-15." (PMID 31360169, 2019). "Recently, IL-15 was shown to induce differentiation of CD105+ renal CSCs isolated from human renal carcinomas." (PMID 27891093, 2016). "IL-15 exhibits a therapeutic index superior to that of IL-2, and is commonly used in renal cancer treatment." (PMID 27891093, 2016). "However, few studies have shown that IL-15 can be expressed by tumor cells, except for human renal cancer cells." (PMID 38637902, 2024). "Additionally, an impact of IL-15 on a progression of renal cancer is suspected, as particular isoforms of this cytokine act as a down-regulator of E-cadherin, resulting in increased risk of cell neoplastic transformation and tumor growth." (PMID 37108157, 2023). "Moreover, IL-15 has been found to participate in the development of solid tumors notably, in renal carcinoma where, stimulation of the membrane-bound IL-15 by soluble IL-15Rα chain favors epithelial to mesenchymal transition." (PMID 22363690, 2012). "Mature myeloid dendritic cells and renal cancer cells were employed as positive and negative controls of IL-15 secretion." (PMID 18493613, 2008).
sarcoma (8 papers, 2015 to 2025). A usually aggressive malignant neoplasm of the soft tissue or bone. "IL-15, a potent activator of NK and T cell anti-tumor activity, was underexpressed in sarcoma cohorts." (PMID 41008853, 2025). "Pan-cancer patients with uterine corpus endometrial carcinoma, sarcoma, cholangiocarcinoma, and esophageal adenocarcinoma owned the highest gene alteration rate of IL-15 (>2%) compared with the primary type in the cBioPortal database." (PMID 36467072, 2022). "NSG.Tg(Hu-IL-15) mice receiving LV/hu-IL-12 transduced sarcomas developed measurable serum IL-12 with corresponding IFN-γ increases while mice receiving non-transduced sarcoma developed no detectable amounts of either cytokine." (PMID 33859303, 2021). "Mice treated with interferon (IFN)-α, IL-2, IL-12, IL-15, or IL-18 showed an increase in NK cell cytotoxicity against multiple sarcoma cell subtypes, but few have been translated successfully to the clinic." (PMID 34804076, 2021). "A phase I clinical trial evaluating the anti-tumor actions of IL-15 is administering autologous ex vivo activated NK cells with or without recombinant IL-15 to patients with solid tumors, including sarcomas (NCT01875601)." (PMID 34440139, 2021). "IL-15 was tested in a phase I clinical trial as a 10-day continuous infusion in 27 adults with advanced metastatic solid tumors, including 4 sarcomas." (PMID 34804076, 2021). "Unsatisfying results of HSCT in sarcoma treatment resulted in further attempts at improving the results by administrating IL-15 activated NK cells after haplo-HSCT for pediatric sarcoma treatment." (PMID 33322371, 2020). "A clinical trial combining recombinant human IL15 with NK cells for relapsed and refractory pediatric solid tumors, including sarcomas, is currently underway at the U.S. National Cancer Institute (NCT01875601)." (PMID 26301204, 2015). "Levels of IL-1β, IL-4, IL-6, CXCL5, CXCL12, CXCL14, MIF, IGF-1, TGFβ-1, and CCL21 were increased in one or more sarcoma cohorts compared with controls, and levels of IL-15 and IL-16 were significantly lower in one or more sarcoma cohorts compared to healthy controls." (PMID 41008853, 2025). "Our in vivo model utilized the humanized transgenic NSG expressing hu-IL-15 with a mature NK cell population and demonstrated a significant restriction of tumor growth only with the introduction of the LV/hu-IL-12 transduced sarcoma." (PMID 33859303, 2021). "In summary, in this transgenic model with endogenous human IL-15 supporting a primary human NK population, a human sarcoma producing hu-IL-12 following lentiviral transduction was able to elicit a specific inflammatory response with significant control of tumor growth." (PMID 33859303, 2021). "Five days of IL-15 pretreatment was able to increase NK cell resistance to sarcoma suppression." (PMID 33322371, 2020). "Several preclinical studies have shown that IL-15 may potentiate anti-sarcoma immunotherapy in Ewing and osteosarcoma models." (PMID 26301204, 2015). "IL-12 expressing sarcomas were assessed in vitro and in vivo following implantation into humanized NSG and transgenic human IL-15 expressing (NSG.Tg(Hu-IL-15)) murine models." (PMID 33859303, 2021). "We conclude that LV/hu-IL-12 transduction of sarcoma elicits a specific immune reaction and the humanized NSG.Tg(Hu-IL-15) xenograft, with mature human NK cells, can define in vivo anti-tumor effects and systemic toxicities." (PMID 33859303, 2021). "No statistical differences were observed in the degree of humanization between the NSG.Tg(Hu-IL-15) mice prior to receiving no sarcoma cells, non-transduced, and LV/hu-IL-12 transduced sarcoma cells." (PMID 33859303, 2021). "No mice in the NSG.Tg(Hu-IL-15) cohort receiving LV/hu-IL-12 transduced sarcoma met stopping criteria for tumor size; mice who met stopping criteria were for weight loss (n = 2) or post blood draw mortality (n = 1)." (PMID 33859303, 2021).
sarcoma (continued). "All mice in the NSG.Tg(Hu-IL-15) cohort receiving non-transduced sarcoma met stopping criteria due to tumor size." (PMID 33859303, 2021). "In orthotopic xenograft murine models, the LV/hu-IL-12 transduced human sarcoma produced detectable IL-12 and elicited an IFN-γ inflammatory immune response specific to mature human NK reconstitution in the NSG.Tg(Hu-IL-15) model while restricting tumor growth." (PMID 33859303, 2021). "Although no clinical trial of IL-15 has been conducted specifically for sarcomas, this cytokine will likely play a major role in future immunotherapy strategies." (PMID 26301204, 2015). "In addition, it has been shown that the cytokine IL-15 modulates the balance between activation and exhaustion by simultaneously promoting cytotoxic function and inducing the expression of inhibitory TIGIT on NK cells in patients with sarcomas." (PMID 38967649, 2024). "NSG.Tg(Hu-IL-15) mice receiving non-transduced sarcoma cells demonstrated significant weight gain relative to mice who received LV/hu-IL-12 transduced sarcoma cells (p = 0.0011) and to mice receiving no sarcoma cells (p = 0.0338)." (PMID 33859303, 2021).
Splenomegaly (8 papers, 2016 to 2024). Abnormal increased size of the spleen. "While NOD.scid mice invariably develop thymoma, lymphadenopathy and splenomegaly are early features in leukemic NOD.scid.Il15−/− mice." (PMID 36765626, 2023). "A similar trend was observed for splenomegaly and hepatomegaly, as well as for changes in IL-15 levels and splenomegaly." (PMID 37243231, 2023).
atopic dermatitis (7 papers, 2018 to 2025). "Atopic dermatitis (AD) patients show deficiency in circulating NK cells and administration of NK cell-boosting IL-15 superagonist leads to clinical amelioration in AD mice." (PMID 35172900, 2022). "Recently, researchers have identified a small subset of skin DCs called mregDCs with high expressions of BIRC3, LAMP3, IL15, CD40, and CCR7, and this subset has been thought to be associated with wound healing and the exacerbation of atopic dermatitis." (PMID 35280984, 2022).
cervical cancer (7 papers, 2013 to 2023). A primary or metastatic malignant neoplasm involving the cervix. "For instance, NKG2A is overexpressed in human cervical cancer cells, and this mechanism is dependent on interleukin -15 (IL-15) to upregulate its expression in CD8+T cells, thus inhibiting the cytotoxicity of lymphocytes and rendering them ineffective in killing tumors." (PMID 37103820, 2023). "Strikingly, HPV vaccine-stimulated IL-15 DC exert cytotoxic activity against HPV16+ and HPV18+ cervical cancer cells, which is synergistically increased when these DC are combined with autologous NK cells." (PMID 24979331, 2014). "We demonstrated that the HPV vaccine can indirectly promote NK-cell immunity via IL-15 DC, illustrated by phenotypic NK-cell activation and synergistically increased cytotoxicity against HPV16+ and HPV18+ cervical cancer cells by Cer-DC/NK-cell co-cultures." (PMID 24979331, 2014). "Moreover, IL-15 generated moDCs, that were matured with a human papilloma virus (HPV) vaccine, demonstrated a Th1-polarized cytokine profile, and increased the cytotoxicity of NK cells against cervical cancer cell lines." (PMID 34054844, 2021). "In addition to the effects on maturation and cytokine secretion, we are the first to demonstrate that the HPV vaccine stimulates the intrinsic innate function of IL-15 DC, resulting in the killing of HPV16+ and HPV18+ cervical cancer cells, but not HPV− K562 cells." (PMID 24979331, 2014).
chronic lymphocytic leukemia (7 papers, 2020 to 2025). "Rapid and impressive responses (ORR: 73% CR: 64%) were achieved with a bicistronic CD19-28-ζ CAR/IL-15 UCB NK cells in chronic lymphocytic leukemia (CLL) and lymphoma refractory and relapsed setting (NCT03056339)." (PMID 35990652, 2022). "Currently, IL-15 is being tested in combination with other mAbs directed against tumor-associated antigens, with Alemtuzumab (anti-CD52) in adult patients with T-cell leukemia (NCT02689453) and Obinutuzumab (anti-CD20) in patients with chronic lymphocyte leukemia (NCT03759184)." (PMID 32605193, 2020).
ischemic stroke (7 papers, 2013 to 2023). A stroke disorder caused by obstruction of blood flow to the brain, due to thrombotic (local blood clot formation) or embolic (due to a blood clot or other material traveling from another site) event. "Astrocytes produce inflammatory cytokines such as IL-15, which promote the cell-mediated immune reaction to ischemic stroke, increase the number of CD8+ T cells and NK cells, participating in ischemic nerve injury." (PMID 35173738, 2022). "Subsequent studies have shown that IL-15 is a key factor for astrocytes to control the degree of central nervous system inflammation and brain injury following ischemic stroke." (PMID 35173738, 2022). "Similarly, astrocytic IL-15 also exacerbates brain damage after ischemic stroke by enhancing cell-mediated immune responses." (PMID 36439158, 2022).
liver fibrosis (7 papers, 2020 to 2025). "IL-15 produced by activated HSCs was shown to promote liver fibrosis by increasing the survival and pathogenic potential of neutrophils." (PMID 38919611, 2024). "Even though the loss of IL-15 or IL-15Rα diminished CCl4-induced liver fibrosis, this reduction was more pronounced in Il15ra–/– mice than in Il15–/– mice." (PMID 38919611, 2024). "Our findings reveal that IL-15 exerts a profibrogenic role in liver fibrosis induced by carbon tetrachloride (CCl4) and its pathogenic effects are largely dependent on IL-15Rα-mediated trans-presentation of IL-15." (PMID 38919611, 2024). "Moreover, the protective role of IL-15 in murine hepatic fibrosis has been linked to its ability, on the one hand, to preserve NK homeostasis and, on the other hand, to directly inhibit the trans-differentiation of hepatic stellate cells into myofibroblasts." (PMID 34769128, 2021). "Similarly, a minor SNP at the 3’-untranslated region of IL15 gene (rs10833 AA instead of GG/GA) increases liver fibrosis risk in HCV/HIV co-infected patients by 2.3-fold via unknown mechanisms." (PMID 38919611, 2024). "We induced liver fibrosis in Il15–/–, Il15ra–/– and wildtype C57BL/6 mice by the administration of carbon tetrachloride (CCl4)." (PMID 38919611, 2024). "Both Il15–/– and Il15ra–/– mice developed markedly reduced liver fibrosis compared to wildtype control mice, as revealed by reduced collagen deposition and myofibroblast content." (PMID 38919611, 2024). "In the present work, we used both Il15–/– and Il15ra–/– mice to understand the role of IL-15 in chemical induced liver fibrosis and the requirement for IL-15Rα in mediating IL-15 signaling during liver fibrosis." (PMID 38919611, 2024). "As myeloid cells play a key role in liver fibrosis and IL-15Rα-independent IL-15 signaling impacts macrophage functions, we examined macrophage infiltration into the livers of CCl4-treated Il15–/–, Il15ra–/–and wildtype mice." (PMID 38919611, 2024). "In this study, we show that IL-15 promotes pathogenesis of liver fibrosis through IL-15Rα-dependent pro-inflammatory macrophage recruitment." (PMID 38919611, 2024). "As myeloid cells are key players in liver fibrosis and IL-15 signaling can occur independently of IL-15Rα, we investigated the requirement of IL-15 and IL-15Rα in liver fibrosis." (PMID 38919611, 2024). "In conclusion, our findings show that IL-15 signaling via IL-15Rα is strongly pro-inflammatory and profibrogenic during liver fibrosis." (PMID 38919611, 2024). "This review highlights a significant increase in infiltrating monocytes in diabetic livers, with hepatic macrophages shifting to a pro-inflammatory state, elevating IFN-γ, TNF-α, IL-1β, IL-15, and IL-18, promoting inflammation, and contributing to liver fibrosis." (PMID 40362271, 2025). "Hence, we tested liver fibrosis development in female Il15–/– and Il15ra–/– mice following CCl4 treatment." (PMID 38919611, 2024). "However, as we observed similarly reduced liver fibrosis both Il15–/– and Il15ra–/– mice under the same experimental settings, our findings strongly support the profibrogenic role of IL-15 signaling in hepatic fibrogenesis." (PMID 38919611, 2024). "Moreover, IL-15 is involved in the progression of liver fibrosis by activating HSCs in patients with viral hepatitis." (PMID 37735474, 2023). "Similarly, IL-15 displays a protective role in murine hepatic fibrosis by preserving NK homeostasis and modulating inflammation but also by directly blocking the myofibroblastic differentiation of hepatic stellate cells." (PMID 34769128, 2021). "Notably, CCl4-treated Il15ra–/– mice showed even less staining of COL1A1 and CD45+ cell infiltration compared to Il15–/– mice, clearly indicating that IL-15 signaling via IL-15Rα-dependent trans-presentation promotes liver fibrosis via promoting inflammatory cell recruitment." (PMID 38919611, 2024). "However, the current literature on the role of IL-15 in liver fibrosis are contradictory." (PMID 38919611, 2024).
liver fibrosis (continued). "A series of studies have shown that CXCL9, IL15 and CCL5 up-regulated significantly in hepatocytes of HCV-infected patients and MASH patients, and existed a correlation between CXCL9 levels and liver fibrosis." (PMID 39605886, 2024). "Moreover, the susceptibility of IL-15 deficient mice to liver fibrosis has not yet been studied." (PMID 38919611, 2024). "In patients co-infected with HCV and HIV, IL-15 expression is correlated to HSC activation and accelerated liver fibrosis." (PMID 38919611, 2024). "However, increased liver fibrosis has been reported in mice lacking IL-15 receptor alpha chain (IL-15Rα), suggesting an anti-fibrogenic role for IL-15." (PMID 38919611, 2024). "However, the paucity of NK cells did not result in increased liver fibrosis CCl4-treated Il15–/– and Il15ra–/– mice in our study." (PMID 38919611, 2024).
myocarditis (7 papers, 2020 to 2025). Myocarditis is a condition that is characterized by inflammation of the heart muscle (myocardium). "In parallel, pericardial/cardiac Trm expand after injury and can drive myocarditis in experimental models, with human pericardial macrophages providing IL-15 that supports Trm maintenance." (PMID 41155153, 2025). "IL-15 is a pleiotropic cytokine suggested to have a protective effect in myocarditis by reducing cardiomyocyte death and improving cardiac function." (PMID 40623042, 2025). "IL‐15 has a positive effect on CVB3‐ induced murine myocarditis and promotes survival in cardiomyocytes." (PMID 32406586, 2020). "So, in viral-induced myocarditis in BALB/c mice, the treatment with IL-15 had a positive effect on the clinical course of myocarditis, significantly improved systolic and diastolic functions of the left ventricle, and also led to a decrease in cellular infiltrates in the myocardium." (PMID 37047399, 2023). "In this study, the pooled AAV9-mediated overexpression of 60 cytokines in a human Coxsackievirus-B3-induced myocarditis mouse model allowed the identification of five cardioprotective interleukins (IL9, IL3, IL4, IL13, and IL15)." (PMID 35508525, 2022). "AAV9-IL9 showed remarkable enrichment over all other interleukins in both Pool 60 and Pool 15, and in combination with IL3, IL4, IL13, and IL15 (Pool 5), significantly improved CVB3-induced myocarditis." (PMID 35508525, 2022).
parasitemia (7 papers, 2012 to 2023). "In mothers of babies congenitally infected with T. cruzi, parasitemia was positively correlated only with IL-15 and inversely correlated with IL-1β." (PMID 38133693, 2023). "Coinciding in IFNγR-/- mice, reduced amounts of pro-inflammatory cytokines IL-15 and TNFα were observed at the time of peak parasitemia (day 6)." (PMID 26070118, 2015). "At day 22, parasitemia levels of approximately 8.0% were seen for the naïve controls (8.07± 3.9%) and the MVA-CSP group (6.7± 4.3%) while the parasitemia was essentially cleared (0.01± 0.01%) for the MVA-CSP/IL15 vaccinated mice." (PMID 26505634, 2015). "Previously, IL-15 was shown to support the early control and resolution of parasitemia in mice infected with P. chabaudi AS parasites." (PMID 26505634, 2015). "Firstly, during the innate response, T. gondii infection triggers the production of inflammatory cytokines IL-1β, IFNα/β, IL-6, IL-12, IL-15, and IL-18, driving NK cell production of IFNγ, resulting in early control of parasite infection by targeting intracellular parasites." (PMID 37018796, 2023). "Moreover, other TLR agonists (e.g. LPS), cytokines (e.g. IFN-α, IL-15) or parasite infection, stimulated macrophages or DCs were also found to activate NK cells by increasing expression of NKG2D ligands, and thus augment NK cell-mediated cytotoxicity to tumor or infected cells." (PMID 22629344, 2012). "These cattle are known to be tolerant to different endemic parasitic diseases, and so the immunity-related genes within the candidate regions identified (e.g. LTA4H, IL7, IL15, FCN, LTA4H and NFAM1) are potential targets of natural selection." (PMID 30114214, 2018). "In mothers of noninfected children, parasitemia showed a positive correlation with the levels of IL-12p70, IL-15, IFN-γ, and TNF-α and a negative correlation with IL-6." (PMID 38133693, 2023). "In T. cruzi-infected nonpregnant women, IL-12p70 IL-15, IFN-γ, and TNF-α levels were positively correlated with parasitemia, whereas IL-10 was not." (PMID 38133693, 2023). "For example, the parasitemia values at day 16 were 20.09 ± 2.1% for non-immunized and 15.5± 4.7% for MVA-CSP vaccinated mice versus 1.9± 0.9% for the MVA-CSP/IL15 group (p = 0.0057)." (PMID 26505634, 2015). "While no statistical differences in parasitemia levels were observed early in the ascending phase, more than 90% reduction in malaria parasitemia was observed at days 16 and 19 after the challenge in mice vaccinated with the MVA-CSP/IL15 construct compared to the other groups." (PMID 26505634, 2015).